CCR7 (C-C motif chemokine receptor 7)
Diseases named in the same sentence as CCR7 in open-access papers (continued):
Sharing a sentence is not in itself a finding about the gene and the disease.
adenocarcinoma (3 papers, 2019 to 2022). A common cancer characterized by the presence of malignant glandular cells. "Additionally, in comparison with normal samples, the expression level of CCR7, CXCL10, IDO1, and MMP9 were increased in phases of adenocarcinoma’s tissue, while the expression level of CXCL9 and VCAM1 were decreased." (PMID 31214045, 2019).
bacterial infection (3 papers, 2012 to 2023). "Particularly monocyte CCR7 may impact the host response during bacterial infection." (PMID 38077404, 2023).
blood cancers (3 papers, 2020 to 2024). "Taken together, there is ample data on target expression and mechanistic rationales as well as sufficient proof of principle and feasibility data that strongly encourage the therapeutic application of anti-CCR7 therapies in blood cancers." (PMID 34778050, 2021). "CCR7 is currently postulated as a potential therapeutic target for some blood cancers and novel antibody(conjugate)-based strategies targeting CCR7 are being evaluated in early-phase clinical trials." (PMID 34778050, 2021). "In this review we provide a summary of insights towards a better understanding in which blood cancers, particularly B-cell, T-cell, and myeloid-cell malignancies, CCR7 mediates which pathogenetic functions." (PMID 34778050, 2021). "Summary of blood cancers with reported CCR7 expression studies (following 2016 WHO classification of blood neoplasms)." (PMID 34778050, 2021). "Here, we review published data to catalogue CCR7 expression across blood cancers and appraise which classical and novel roles are attributed to this receptor in the pathogenesis of specific hematologic neoplasms." (PMID 34778050, 2021). "Even though, this is the first time that such a correlation is presented in blood cancers that makes CCR7 a reasonable therapeutic target in T-PLL." (PMID 33110606, 2020). "Therefore, interfering in CCR7-signalling promises to be of therapeutic potential in many CCR7 expressing and CCR7 promoted blood cancers." (PMID 34778050, 2021). "We outline why novel therapeutic strategies targeting CCR7 might provide clinical benefits to patients with CCR7-positive hematopoietic tumors." (PMID 34778050, 2021). "Generally, in most blood cancers, CCR7 expression correlates with nodal or spleen involvement." (PMID 34778050, 2021). "CCR7 and CD62L, as well as their corresponding ligands, are known to have an essential function in distinct blood cancers and the metastatic spread of solid tumor cells through the LNs35–38." (PMID 38769377, 2024). "The role(s) of biased signaling of CCR7 in the pathophysiology of blood cancers is not clear, although a scarce number of studies comparing CCR7 activation in healthy versus malignant cells indicate that a differential regulation is plausible." (PMID 34778050, 2021).
head and neck tumors (2 papers, 2019 to 2023). "The importance of the signaling way Janus activated kinase-3 (Jak3) in the metastasis of malignant head and neck tumors mediated by CCR7 and its ligands, can be a new target for treatment of these patients." (PMID 31011147, 2019).
heart disease (2 papers, 2016 to 2023). "Analysis of the chemokine receptor CCR7 for lymph node homing (CCR7 expression) also revealed a significant increase in total effector/memory CD8 T cells in subjects with mild heart disease compared with healthy controls." (PMID 27563302, 2016).
infectious disease (2 papers, 2022 to 2023). A disorder directly resulting from the presence and activity of a microbial, viral, or parasitic agent in humans. "Since delayed migration of Mtb-infected migratory DCs impairs the development of adaptive immunity, identifying the mechanisms that regulate CCR7-dependent migration in infectious disease may help to inform the design of new therapeutics and improved vaccines and requires further investigation." (PMID 37475964, 2023).
animal disease (1 paper, 2022). "For instance, CCR1, CCR7, or CXCR4 modification was found to enhance the migration of MSCs to the injured myocardium, secondary lymphoid organs, and infarcted myocardium, respectively, and to promote recovery in animal disease models." (PMID 35123561, 2022).
hematological cancers (1 paper, 2013). "Therefore, CCR7 may represent a new therapeutic target for the treatment of certain hematological cancers, in particular MCL and CLL." (PMID 24305507, 2013).
inflammatory myopathy (1 paper, 2022). "Neither gene expression of CCR7 nor CXCR4 was elevated in ASyS or IMNM patients (an acute inflammatory myopathy serving as DC) compared to NDC, while CXCL12 expression was elevated in PL-7+ patients when compared to Jo-1+ patients." (PMID 35612662, 2022).
metabolic disorders (1 paper, 2022). "CCR7-/- Treg cells alway accumulate in the effector or inflammatory local to exert immediate effect and exacerbate metabolic disorders of microflora." (PMID 35832382, 2022).
neurological diseases (1 paper, 2009). "We could not identify statistical significant differences within these T-cell subsets, defined by CD45RA and CCR7 expression, which segregate healthy individuals and individuals with neurological diseases." (PMID 19657390, 2009).
renal disease (1 paper, 2022). "Although CCR7+ Tregs provide protection against renal autoimmunity, they do not home to the kidneys, which may explain why we did not see an association between their frequency and active renal disease." (PMID 36381498, 2022).
retinopathy (1 paper, 2023). "CCR7 significantly enhanced neovascularization and the non-perfusion area in oxygen-induced retinopathy." (PMID 36658547, 2023).
CCR7 also shares sentences with these, for which no sentence is quoted: kidney (5 papers); dengue (4); metastatic carcinoma (4); multiple myeloma (4); acute myeloid leukemia (3); hyperlipidemia (3); juvenile idiopathic arthritis (3); periodontitis (3); renal cell carcinoma (3); T-cell prolymphocytic leukemia (3); Anxiety (2); autoimmune uveitis (2); fibrosarcoma (2); gastritis (2); gastrointestinal stromal tumor (2); idiopathic pulmonary fibrosis (2); inflammation (2); inflammatory breast carcinoma (2); interstitial lung disease (2); keloid (2); liver fibrosis (2); malignant glioma (2); Miscarriage (2); neck cancers (2); ovarian tumors (2); Primary immunodeficiency (2); rectal cancer (2); systemic sclerosis (2); Type 2 Diabetes (2); adenosquamous carcinoma (1).
A further 81 diseases each share a sentence with CCR7 in 1 paper.